TNF (tumor necrosis factor)
Diseases named in the same sentence as TNF in open-access papers (continued):
Sharing a sentence is not in itself a finding about the gene and the disease.
colorectal cancer (continued). "The correlations of pretreatment serum concentrations of proinflammatory cytokines such as interleukin (IL)‐1β, IL‐6, and tumor necrosis factor‐α (TNFα) with the clinicopathologic features and progression of colorectal cancer (CRC) were investigated." (PMID 26799163, 2016). "In this study, we show that subtoxic doses of metformin effectively sensitize human colorectal cancer (CRC) cells to tumor necrosis factor (TNF)-related apoptosis-inducing ligand (TRAIL), which induces apoptosis." (PMID 27517746, 2016). "The human colorectal cancer HT29 cells were left untreated or treated with the combination of TNF (T), Smac mimetic (S) and the pan-caspase inhibitor z-VAD-fmk (Z)." (PMID 26866270, 2016). "Recent studies showed that Fusobacterium species increase production of reactive oxygen species (ROS) and inflammatory cytokines (e.g., IL-6 and TNF) in colorectal cancer." (PMID 25797243, 2015). "Here we reported that high expression of microRNA-19a (miR-19a) was associated with lymph node metastasis and played an important role in TNF-α-induced EMT in colorectal cancer (CRC) cells." (PMID 26302825, 2015). "Colorectal cancer patients had increased serum levels of IL-6, IL-1beta, TNF-alpha, and IL-8 but lower IL-10 concentrations." (PMID 26300773, 2015). "Proinflammatory cytokines (IL-1β, IL-6, IL-8, and TNF-α) are elevated in colorectal cancer (CRC), showing the presence of an active and permanent inflammatory state." (PMID 25945105, 2015). "The expression levels of TLR2, TLR4, NF-κB and TNF-α in colorectal cancer and adenoma were also higher than those in the control tissues." (PMID 25435993, 2015). "TNF-α produced by leukocyte was up-regulated in the colorectal carcinoma, and blocking the expression of TNF-α in mice can reduces colorectal carcinogenesis." (PMID 26526388, 2015). "Immunohistochemical analysis revealed that the expression of IE1–72, TLR2, TLR4, NF-κB and TNF-α protein in colorectal carcinoma was significantly higher than that in the normal tissues." (PMID 25435993, 2015). "Glycogen synthase kinase (GSK)-3β-mediated stabilization of Snail is not only part of the Wnt signaling cascade but is also required in colorectal cancer cells for EMT induced by the pro-inflammatory cytokine tumor necrosis factor (TNF)-α." (PMID 25566498, 2014). "In summary, this meta-analysis had pooled all the available data related to TNF-a polymorphisms and colorectal cancer, and indicated that TNF-a 308 was moderately associated with an increased risk of colorectal cancer in Western populations." (PMID 24404201, 2014). "TNF-α induces Met transcription via NF-κB and in human colorectal cancer tissues high levels of TNF-α correlate with increased Met and HGF expression, responsible for HGF/Met pro-invasive paracrine circuits in these tumors." (PMID 28548074, 2014). "Its AKT/GSK-3β-mediated stabilization has been demonstrated to be necessary for TNF-α-induced EMT in colorectal cancer cells." (PMID 24811539, 2014). "Tumor necrosis factor-alpha (TNF-a) was related to inflammation and involved in the development of colorectal cancer." (PMID 24404201, 2014). "TNFα and IL-17 also cooperatively stimulated glucose utilization by three other human colorectal cancer cell lines, HCT116, T84 and Caco-2." (PMID 23866118, 2013). "The transcription factor NF-κB is an important mediator of transcriptional effects of TNFα in target cells including colorectal cancer cells." (PMID 23866118, 2013). "Myofibroblasts, TNF-α, LPA, EGFR, and COX-2 have all been strongly and independently implicated in the development of colorectal cancer." (PMID 23688423, 2013). "Several studies have documented that TNFα activates NF-κB in HT-29 and other human colorectal cancer cell lines." (PMID 23866118, 2013). "The effect of TNFα and IL-17 on aerobic glycolysis and growth factor production in cultured human colorectal cancer cells was investigated." (PMID 23866118, 2013).
colorectal cancer (continued). "In the present study we examined the effect of TNFα and IL-17 on glycolysis and growth factor production in colorectal cancer cells." (PMID 23866118, 2013). "We therefore focused on the analysis of laminin-332 expression in response to cytokines TGFβ and TNFα in cell models adequate to reflect the molecular progression of colorectal cancer in vitro." (PMID 20307265, 2010). "Using this library, we identify a range of small RNA-encoding gene inserts that overcome resistance to 5-fluorouracil (5-FU)- or tumour necrosis factor alpha (TNF-α)- induced cell death in colorectal cancer cells." (PMID 19270743, 2009). "In the present study, we compared the frequency of a series of polymorphisms in different inflammatory response genes associated with IBD (DLG5, IL-4, OCTN, TNFα and NOD2) in colorectal cancer cases against controls." (PMID 18433468, 2008). "CT-26 murine colorectal carcinoma cells were stimulated with LPS, tumour necrosis factor α (TNF-α) and interleukin 6 (IL-6)." (PMID 17242699, 2007). "Long-term follow-up was performed on 40 patients with colorectal cancer who had levels of tumour necrosis factor (TNF)-α, interferon (IFN)-γ and interleukin (IL)-10 measured from stimulated blood cultures before surgery." (PMID 16641913, 2006). "We have previously shown that the strong induction of TNF-α in ex vivo cultures correlates with a better prognosis in patients with colorectal cancer." (PMID 14997189, 2004). "Monocytes/macrophages from patients with colorectal carcinoma are refractory to LPS stimulation as reflected by reduction in TNF-α and IFN-γ production and this is more pronounced in patients with advanced stage tumours." (PMID 10737381, 2000). "Collectively, these data establish that pharmacological modulation of the PAR-2/ERK/TNF-α axis by statins redirects inflammatory colorectal cancer cells from survival toward programmed cell death, with rosuvastatin demonstrating consistently greater potency than atorvastatin." (PMID 41596561, 2026). "Similarly, TNF-α levels were increased in a dose-dependent manner, indicating that P. aeruginosa enhances proinflammatory cytokine production in colorectal cancer cells." (PMID 41484455, 2026). "Moreover, colorectal cancer patients exhibiting higher TNF - α levels typically experienced less favorable outcomes than those with lower concentrations." (PMID 39980561, 2025). "This study also suggests that oxidative stress and inflammation, particularly elevated MDA and TNF-α levels, may play a significant role in the pathophysiology of colorectal cancer among untreated individuals." (PMID 41042771, 2025). "However, in the TME of colorectal cancer, elevated levels of TNF-α have been recognized to play a role in tumor progression and metastasis." (PMID 40558596, 2025). "Related to this, an increase in Akkermansia muciniphila following antibiotic treatment was found to elevate mRNA levels of pro-inflammatory cytokines IL-1β, IL-6 and TNF-α, promoting uncontrolled cellular proliferation and furthering colorectal cancer progression." (PMID 40520902, 2025). "Additionally, clinical data showed that plasma levels of IL-1β, IL-6, and TNF-α are significantly elevated in patients with colorectal cancer compared with healthy controls." (PMID 41463421, 2025). "Additionally, TNF-α inhibitors including infliximab, adalimumab, and etanercept have been shown to reduce inflammation and tumor growth in colorectal cancer models." (PMID 40558596, 2025). "In colorectal cancer cells, TNF-α modulates Panx1 activation to promote ATP release." (PMID 40978734, 2025).
colorectal cancer (continued). "Furthermore, it was recently shown that dysfunctional autophagy increases programmed cell death induced by IFN-γ and TNF and consequently increases the host immunity to colorectal cancer cells." (PMID 41057521, 2025). "Reducing IL-6 and TNF-α expression and infiltration of pro-inflammatory macrophages, remodeling gut microbiota composition and bile acid metabolism to inhibit the TLR4/MyD 88 pathway, and thereby inhibiting colorectal cancer associated with a high-fat diet." (PMID 40066456, 2025). "In colorectal cancer, high levels of TNF-α may promote tumor growth and spread, activate the NF-κB signaling pathway, enhance cell proliferation, and inhibit apoptosis." (PMID 40292300, 2025). "Produces pro-inflammatory cytokines like IL-6 and TNF-α in specific conditions (e.g. colorectal cancer).Creates a pro-inflammatory microenvironment but may also impact adaptive immunity in disease states." (PMID 41050659, 2025). "A previously published study reported the anti-tumor properties of a MIM employing LD and ULD of cytokines such as IFN-α and IL-2 in association with other actives, like tumor necrosis factor (TNF)-α at 5 CH, specifically in the context of colorectal cancer (CRC)." (PMID 40362536, 2025). "TNF-α is well known for its capacity to destroy tumors and was known as cachexin due to this function; however, this cytokine has a complex role in the tumor microenvironment of colorectal carcinoma (CRC)." (PMID 40558596, 2025). "This organ protection measure in patients undergoing laparoscopic colorectal cancer resection decreased the incidence of postoperative gastrointestinal dysfunction and lowered the IL-6, TNF-α, and I-FABP levels, demonstrating protective effect on patients’ postoperative gastrointestinal function." (PMID 39202020, 2024). "TNF-α and IL-8 are cytokines that bind to the TNF and CXC chemokine receptors, respectively to initiate the NF-κB signaling pathway, which causes the angiogenesis of colorectal cancer." (PMID 39301125, 2024). "Mgat5 glycans affect sensitivity to TNF-α–mediated cell death in lung and colorectal cancer cells." (PMID 38912584, 2024). "Interestingly, Smyd-2 has been shown to promote tumor growth in Ovarian Clear-Cell Carcinoma (OCCC) and Colorectal Cancer (CRC) by inhibiting TNF-induced apoptosis." (PMID 39682718, 2024). "Since TNF-α is often present in TDEs, for example, in colorectal carcinoma, there may be a beneficial effect of decreasing TNF-α in anti-cancer therapy." (PMID 38200509, 2024). "Similarly, the expression of cytokines TNF-α, IL-1, and IL-6 was found to be increased in drug-resistant colorectal cancer in the blood samples of each group of xenograft mouse models." (PMID 36840009, 2023). "Anti-interleukin agents may have a positive effect on colorectal cancer, considering the presence of IL-1β, IL-6, and TNF-α in this neoplasia, which was also demonstrated in this prospective study." (PMID 38137862, 2023). "Interestingly, although TNF- α has anti-tumor effect, even some studies have shown that TNF- α can promote tumor cell apoptosis and inhibit tumor liver metastasis in colorectal cancer." (PMID 37006260, 2023). "Furthermore, colorectal cancer cells are capable of producing IL-17, IL-33, TNF-α, and TGF-β to guide IL-17R/ST2/ TNF-αR/ TGF-βR positive neutrophils directional migration." (PMID 37158964, 2023). "In this study, it was shown that IL-1β, IL-6, and TNF-α are present from the early stages of colorectal cancer compared to the control group, and the levels could be used for diagnostic purposes." (PMID 38137862, 2023). "Leptin significantly increases tumor necrosis factor alpha (TNF-α) secretion through the activation of p38 and JNK/MAPK and TNF-α can induce cancer invasion and metastasis associated with EMT in colorectal cancer, suggesting a potential effect of leptin on EMT in colorectal cancer as well." (PMID 37686525, 2023).
colorectal cancer (continued). "A previous study indicated that PA showed anti‐inflammatory activity by downregulating the extracellular signal‐regulated kinase (ERK)‐mediated nuclear factor kappa B (NF‐κB) pathway in tumour necrosis factor (TNF)‐α‐stimulated HT‐29 human colorectal cancer cells." (PMID 37038620, 2023). "Sixty-one signal pathways were obtained by introducing the potential targets into the DAVID database, mainly related to neuroactive ligand-receptor interaction, colorectal cancer, influenza A, TNF signaling pathway, cAMP signaling pathway, Rap1 signaling pathway, and so on." (PMID 36173042, 2023). "To test whether Pol III inhibition sensitises colorectal cancer cells to TNFα treatment, we first investigated the viability of cells using an MTT colorimetric assay." (PMID 36900285, 2023). "Additionally, co-localisation of TNF-α and miR-21 expression, particularly at the tumour leading edge, of colorectal cancer has been reported." (PMID 36765584, 2023). "In a recent study from France, the risk of colorectal cancer was only reduced in patients with long-standing colitis (more than 10 years) (HR 0.41; 95% CI, 0.20–0.86) and not in all patients treated with anti-TNF." (PMID 37190315, 2023). "TNF-α was found to induce colorectal cancer cell migration and EMT via activating AKT signaling." (PMID 37124061, 2023). "GVM appears to be safe and effective for alleviating CRF in patients who have completed colorectal cancer treatment, which may be related to the modulation of IL-6 and TNF-α levels." (PMID 37397368, 2023). "In addition, it was found that miR-539 was low expressed in colorectal cancer, while tumor necrosis factor (TNF)- α Induced protein 8 (TNFAIP8/TIP8) is highly expressed in colorectal cancer." (PMID 36408273, 2022). "Further, TNF-α paracrine and autocrine activity induced cell death in colorectal cancer." (PMID 35341150, 2022). "Chronically inflamed adipocytes play a key role in this pathologic process by secreting pro-inflammatory cytokines, such as interleukin-1β, -6, and tumor necrosis factor-α which are relevant for the pathogenesis of certain neoplasms (colorectal cancers among others)." (PMID 35205684, 2022). "IL-6/IL-8/TNF levels after operation among colorectal cancer patients in the four groups." (PMID 35479322, 2022). "Moreover, the increased levels of IL-6 and TNF-α following 5-FU-treated colorectal cancer cells have been reported." (PMID 35366874, 2022). "There has been no randomized controlled trial that was conducted to test the efficacy of anti-TNF drugs in the prevention of colorectal cancer, leading to uncertainty about whether anti-TNF drugs are beneficial for reducing the risk of colorectal cancer." (PMID 36618924, 2022). "miR-31 transcription activated in colorectal cancer cells in response to TNF-α and IL-6." (PMID 35967345, 2022). "First, the drug-target mendelian randomization design could only determine whether TNF inhibition had a protective effect on colorectal cancer." (PMID 36618924, 2022). "In addition, the results of the KEGG pathway enrichment analysis mainly included Apoptosis, Colorectal cancer, IL-17 signaling pathway, TNF signaling pathway, Human immunodeficiency virus 1 infection, HIF-1 signaling pathway." (PMID 35677450, 2022). "Lactobacillus rhamnosus GG and its secreted components exhibited anti-inflammatory and anti-apoptotic actions in colon epithelial cells by reducing TNF-α-induced apoptosis in HT-29 human colorectal cancer cells and ameliorating TNF-α-induced epithelial damage in mouse colon explants." (PMID 36140470, 2022). "Notably, colorectal cancer has been shown to exhibit extensive inflammatory infiltrates with high levels of cytokine expression in the tumor microenvironment and TNF can activate NF-κB to promote colorectal cancer cell growth." (PMID 35222445, 2022).
colorectal cancer (continued). "The relationship between the levels and the clinical characteristics of patients was observed; the factors affecting the levels of IL-6, TNF-α, and IL-12p70 in colorectal cancer patients were analyzed, and the predictive validity of the efficacy of anti-vascular therapy was evaluated." (PMID 36226059, 2022). "Colorectal cancer is accompanied by an increase in tumor necrosis factor alpha (TNFα) and interleukin 10 (IL10) that exert opposite regulatory effects on barrier properties of the colon, which is characterized by morphological and functional segmental heterogeneity." (PMID 36555251, 2022). "In the current review, we found that a randomized controlled study reported that L-carnosine exerted neuroprotective activity by significantly decreasing proinflammatory (NF-κB, TNF-α) and apoptotic (caspase-3) markers and increasing Nrf2 in colorectal cancer patients with oxaliplatin-induced PN." (PMID 35204312, 2022). "Physicians could consider using anti-TNF drugs for the prevention of colorectal cancer, especially in patients with high risks of developing cancer." (PMID 36618924, 2022). "The coordinated expression of CCL5 with TNF-α in our research may point to an inflammatory network between chemokines and cytokines in colorectal cancer and can be associated with the promotion of CCL5 secretion by TNF-α." (PMID 35208526, 2022). "Importantly, roburic acid inhibited the TNF-induced NF-κB signaling pathway and suppressed the expression of these antiapoptotic proteins in colorectal cancer cells." (PMID 35222445, 2022). "The evidence from previously published studies and our study supported that the utilization of anti-TNF drugs might be a potential chemoprevention method for colorectal cancer." (PMID 36618924, 2022). "Many studies have pointed to the significant role of TNFα in colorectal cancer development." (PMID 35208526, 2022). "We aimed to analyze the levels of interleukin-6 (IL-6), tumor necrosis factor-α (TNF-α) and interleukin-12 (IL-12p70) in colorectal cancer and evaluate the predictive significance of clinical efficacy of patients with colorectal cancer treated with anti-vascular therapy combined with chemotherapy." (PMID 36226059, 2022). "IL-6/IL-8/TNF levels before operation among colorectal cancer patients in the four groups." (PMID 35479322, 2022). "Furthermore, in this study, the same bacteria that correlated with IL-6, CRP, and TNF-α levels in the GI microbiota dysbiosis mice have been detected in fecal and tumor samples of patients with breast, cervical, and colorectal cancer." (PMID 35740687, 2022). "A few studies demonstrate the dual role of TNF-α in colorectal carcinoma." (PMID 35954156, 2022). "A study investigating the impact of 5-FU chemotherapy on gut inflammation showed that in AOM/DSS-induced colorectal cancer model mouse treated with 5FU, significantly elevated expression of intestinal inflammatory genes was found, including TNF-α, MCP-1, NOS2, IL6, IL1-β, and FOXP3." (PMID 34337082, 2021). "RAP2C has also been reported to be involved in TNF-α-induced colorectal cancer metastasis." (PMID 34122424, 2021). "While treatment with TNF/SMAC mimetic (SM)/z-VAD-FMK (TSZ) caused time- and RIPK1-dependent necroptosis in human colorectal cancer HT-29 cells, mouse dermal fibroblasts (MDFs) and murine L929 cells, TSZ also triggered ubiquitylation of endogenous MLKL in all these cell types." (PMID 34099649, 2021). "In addition to PGE2, numerous inflammatory cytokines have also been shown to be involved in initiation, and progression of colorectal cancers, such as tumor necrosis factor α (TNF-α), and interleukin 6 (IL-6)." (PMID 34267186, 2021). "In addition, TNF is involved in colorectal cancer progression via the induction of miR-105, which modulates the epithelial–mesenchymal transition." (PMID 33917839, 2021). "However, a decrease in TNF-α expression in plasma and the colon was reported after 6 weeks of regular running in a mouse model of colorectal cancer." (PMID 32309219, 2020).